EIF4A1 (eukaryotic translation initiation factor 4A1)
Diseases named in the same sentence as EIF4A1 in open-access papers (continued):
Sharing a sentence is not in itself a finding about the gene and the disease.
glioma (4 papers, 2013 to 2023). A benign or malignant brain and spinal cord tumor that arises from glial cells (astrocytes, oligodendrocytes, ependymal cells). "As eIF4H and its interaction partner eIF4A1 seem to be relevant in gliomas, inhibiting the interaction between those two factors might be a novel approach in glioma therapy." (PMID 33807050, 2021). "Protein and mRNA expressions of eIF3B, eIF3I, eIF4A1, eIF4H, eIF5 and eIF6 were significantly increased in high grade gliomas compared to CCBT and partially in low grade gliomas." (PMID 33807050, 2021).
prostate carcinoma (4 papers, 2017 to 2023). A carcinoma that arises from epithelial cells of the prostate gland. "PKP1 associates with eukaryotic translation initiation factor 4A1 to stimulate protein translation and loss of PKP1 is linked to prostate cancer proliferation." (PMID 29052507, 2017).
COVID-19 (3 papers, 2021 to 2023). A disease caused by infection with severe acute respiratory syndrome coronavirus 2. "The correlations of the COVID-19-dependent platelet proteins EIF4A1 and TALDO1 with the viral load of the patients also suggest a direct replication of the virus in platelets." (PMID 34859078, 2021). "With a significant increase in EIF4A1 in platelets of COVID-19 patients, we identified another protein that may be directly related to viral RNA translation." (PMID 34859078, 2021). "Furthermore, we also found a significant correlation between the amount of EIF4A1 in platelets and nasopharyngeal viral load of COVID-19 patients (rS = 0.598; p = 0.009; n = 18)." (PMID 34859078, 2021). "Depending on COVID-19 disease status and mortality, increased amounts of annexin A5 (ANXA5), eukaryotic initiation factor 4A-I (EIF4A1), and transaldolase (TALDO1) were found in the platelet proteome and also correlated with the nasopharyngeal viral load." (PMID 34859078, 2021). "At the same time, levels in non-survivors remained stable, resulting in significantly increased levels of EIF4A1 in the non-surviving COVID-19 patients compared to the survivors on days 4–5 (FC = 1.41; p = 0.019)." (PMID 34859078, 2021). "However, the significant changes regarding increased levels of ANXA5, EIF4A1 and TALDO1 are so far unique for the platelet proteome of COVID-19 patients." (PMID 34859078, 2021).
diffuse large B-cell lymphoma (3 papers, 2021 to 2025). "Expression of eIF4A1 is significantly upregulated in diffuse large B-cell lymphoma (DLBCL), which is predictive of poor patient prognosis." (PMID 39516355, 2025). "eIF4A1 was highly expressed in multiple cancer types, including pancreatic adenocarcinoma, thymoma, glioblastoma multiforme, diffuse large B cell lymphoma, and testicular germ cell tumors." (PMID 34906136, 2021).
glioblastoma (3 papers, 2013 to 2023). The most malignant astrocytic tumor (WHO grade IV). "As Markov blanket genes, DUSP1 was common in Pilocytic and Diffuse tumors; EIF4A1 was common in Pilocytic, Diffuse and Anaplastic tumors; MARCKs was common in Diffuse and Anaplastic tumors and SERBP common in Anaplastic and Glioblastoma tumors." (PMID 23737970, 2013). "eIF4A1 mRNA expression was elevated in various cancer types, including colon adenocarcinoma (COAD), glioblastoma multiforme (GBM), esophageal carcinoma (ESCA), and kidney renal clear cell carcinoma (KIRC), among others." (PMID 36768380, 2023).
lung adenocarcinoma (3 papers, 2022 to 2026). A carcinoma that arises from the lung and is characterized by the presence of malignant glandular epithelial cells. "The results specify EIF4A1 in lung adenocarcinoma tumorigenesis." (PMID 36101357, 2022).
osteosarcoma (3 papers, 2022 to 2025). A usually aggressive malignant bone-forming mesenchymal neoplasm, predominantly affecting adolescents and young adults. "CR-1-31B, a rocaglate-based EIF4A1 inhibitor, potently inhibited osteosarcoma growth in a pulmonary metastasis assay and in experimental and spontaneous models of lung metastasis." (PMID 40507333, 2025). "We showed that human and dog osteosarcoma cells expressed high levels of eIF4A1/2, particularly eIF4A2." (PMID 38947012, 2024). "Genetic depletion of eIF4A1 and/or 2 slowed osteosarcoma cell growth." (PMID 38947012, 2024). "In addition, the clinical-grade EIF4A1 Phase-1-to-2 inhibitor, zotatifin, similarly blocked NRF2 synthesis and osteosarcoma metastasis." (PMID 40507333, 2025).
Astrocytoma (2 papers, 2013 to 2021). "We showed that the expression of eIF3B, eIF3I, eIF4A1, eIF4H and eIF6 was significantly increased in astrocytomas, in particular in GBM, for protein and mRNA levels." (PMID 33807050, 2021). "Significantly elevated protein levels were found for eIF4A1 (I: p < 0.01, II: p < 0.01, III: p < 0.001, IV: p < 0.001) and p-eIF4G (I: p < 0.01, II: p < 0.05, III: p < 0.01, IV: p < 0.01) in astrocytomas compared to CCBT." (PMID 33807050, 2021).
leukemia (2 papers, 2021 to 2022). A malignant (clonal) hematologic disorder, involving hematopoietic stem cells and characterized by the presence of primitive or atypical myeloid or lymphoid cells in the bone marrow and the blood. "According to these reports, USP15 played indispensable roles in many diseases such as safeguarding genome integrity in leukemia cells, promoting the apoptosis of degenerative nucleus pulposus cells, and enhancing re-epithelialization through deubiquitinating EIF4A1 during cutaneous wound repair." (PMID 33726807, 2021).
lung carcinoma (2 papers, 2021 to 2022). "Our study indicates that EIF4A1 acts as an oncogene in lung cancer development." (PMID 36101357, 2022). "Notably, the survival analyses from the KM plotter revealed lower overall survival time (OS) and post-progression survival (PPS) but not time to first progression (FP) in lung cancer patients with high EIF4A1 expression as well as expression of its correlated genes." (PMID 36101357, 2022). "To identify if EIF4A1 and EIF4A2 expression were correlated with lung cancer development, we assessed the expression of both genes in normal and LUAD tumor tissue using a TCGA cohort." (PMID 36101357, 2022).
metastatic tumor (2 papers, 2015 to 2024). "Accordingly, elevated expression of RPs and Eif4a1 was also detected in both prostate primary and metastatic tumor cells, aligning with upregulated XPO1, HGF/MET, and Wnt/β-catenin downstream target expression." (PMID 38336745, 2024). "We detected eukaryotic translation initiation factor 4A-1, encoded by the related EIF4A1 gene on chromosome 17, in 5 metastatic and 4 non-metastatic tumors and to be significantly elevated only in metastatic tumors." (PMID 26305875, 2015).
neuroblastoma (2 papers, 2021 to 2025). Neuroblastoma (NB) is the most common solid, extracranial childhood tumor. "is a preclinical in vitro investigation that explores the potential of targeting eIF4A1 as a novel therapeutic approach for neuroblastoma." (PMID 40104501, 2025). "They found that eIF4A1 is overexpressed in neuroblastoma tissues, contributing to tumorigenesis through its role in translation initiation." (PMID 40104501, 2025). "By using the synthetic rocaglate CR-1-31-B, which clamps eIF4A1 to mRNA and inhibits translation initiation, they observed decreased cell viability, increased apoptosis, and alterations in cell cycle distribution in neuroblastoma cell lines." (PMID 40104501, 2025).
ovarian carcinoma (2 papers, 2021 to 2025). A malignant neoplasm originating from the surface ovarian epithelium. "We also compared our proteomic data with the ExoCarta database and identified the presence of both eIF4E and eIF4A1 in EVs derived from ovarian cancer cells." (PMID 40820860, 2025). "eIF4E and eIF4A1 were also present in EVs isolated from multiple human and murine ovarian cancer cell lines." (PMID 40820860, 2025). "Moreover, a significant increase in the expression of eIF4E and eIF4A1 in EVs from the plasma and ascites of ovarian cancer patients was observed, compared to EVs from the plasma and pelvic wash of healthy donors." (PMID 40820860, 2025).
pancreatic adenocarcinoma (2 papers, 2021). "In summary, these results showed that eIF4A1 was highly expressed in pancreatic adenocarcinoma tissues, and high expression of eIF4A1 suggested a poor prognosis." (PMID 34906136, 2021). "eIF4A1 also showed significant positive correlations with dendritic cells, CD8+ T cells, and neutrophils in BLCA, KICH, KIRC, LIHC, pancreatic adenocarcinoma (PAAD), pheochromocytoma and paraganglioma (PCPG), and thymoma (THYM)." (PMID 34869305, 2021).
breast tumors (1 paper, 2015). "Therefore, immunohistochemical analysis was performed on over 3000 breast tumors to investigate the relationship among expression of eIF4A1, the helicase-modulating proteins eIF4B, eIF4E and PDCD4, and clinical outcome." (PMID 25611378, 2015).
cervical tumor (1 paper, 2024). "The non-degradative ubiquitination of eIF4A1 catalyzed by the CRL3IBTK complex promotes cap-dependent translational initiation, nascent protein synthesis, oncogene expression, and cervical tumor cell growth both in vivo and in vitro." (PMID 38738857, 2024).
colorectal tumor (1 paper, 2021). "In our study, EIF4A1 mRNA level in colorectal tumor tissues decreased compared to the control group, while it increased in peripheral blood compared to the control group." (PMID 33237662, 2021).
cutaneous squamous cell carcinoma (1 paper, 2023). "Combined inhibition of the Raf/MAPK/extracellular signaling-regulated kinase axis and eIF4A1 decreased the 5′-capsule-dependent translational process and attenuated the growth, metastasis, and invasiveness of cutaneous squamous cell carcinoma cells." (PMID 38028556, 2023).
dementia (1 paper, 2024). Loss of intellectual abilities interfering with an individual's social and occupational functions. "Four protective proteins (PLEK, DAPP1, CSK and CASP3) that decreased postinfection in the BLSA were significantly decreased in dementia cases in the ARIC study, with several other protective proteins (EIF4A1, DSG1, PIK3CG, PRKCB and LYN) showing similar trends." (PMID 39143319, 2024).
epilepsy (1 paper, 2025). A brain disorder characterized by episodes of abnormally increased neuronal discharge resulting in transient episodes of sensory or motor neurological dysfunction, or psychic dysfunction. "The cytological connection between eIF4E3, EIF4A1, and the beginning of epilepsy still need more research." (PMID 40658715, 2025). "The boxplot revealed that epilepsy patients had up-regulated expression levels of NUDT3, EIF4E3, LARP1, IFIT5, and SNUPN, and down-regulated expression levels of METTL1, EIF4A1, and LSM1." (PMID 40658715, 2025). "Gene expression analysis of datasets GSE143272 and GSE190452 identified 8 differentially expressed m7G regulators (NUDT3, EIF4E3, LARP1, IFIT5, SNUPN, METTL1, EIF4A1, and LSM1) in epilepsy." (PMID 40658715, 2025).
kidney tumor (1 paper, 2020). "We employed immunohistochemistry results from the HPA database to discover that EIF4A1 was significantly increased in kidney tumor tissue compared with normal tissue." (PMID 33133154, 2020).
primary immunodeficiency (1 paper, 2023). "In this study, we have identified four enriched crosstalk genes in primary immunodeficiency, Interferon type I signalling, and translation factors pathways; that is, LCK, PTPRC, EIF4A1, and EIF4EBP1." (PMID 37277696, 2023).
sarcoma (1 paper, 2023). A usually aggressive malignant neoplasm of the soft tissue or bone. "Sarcoma patients were divided into two groups according to the risk scores, survival status, and the expression of EIF4A1, EIF4G3, NCBP1, and WDR4." (PMID 36816047, 2023). "Risk score = (0.1472) *EIF4A1 + (0.4087)*EIF4G3 (−0.2538)*NCBP1 + (0.6578)*WDR4 was applied to the calculation of OS in sarcoma patients." (PMID 36816047, 2023). "Patients with sarcoma who had high levels of EIF4A1, EIF4G3, NCBP1, and WDR4 exhibited a lower OS rate." (PMID 36816047, 2023). "Theoretically, miRNAs that bind to high expression EIF4A1, EIF4G3, NCBP1, and WDR4 should be down regulated in sarcomas and show poor prognosis." (PMID 36816047, 2023). "The correlation between the expression of prognostic m7GRGs (EIF4A1, EIF4G3, NCBP1, WDR4) and immune infiltration in sarcomas was investigated using the TIMER database and TCGA database." (PMID 36816047, 2023). "Besides, we constructed a prognostic model that consists of EIF4A1, EIF4G3, NCBP1, and WDR4 m7GRGs for predicting the survival likelihood of sarcoma patients." (PMID 36816047, 2023). "According to TIMER data, EIF4G3, and NCBP1 were negatively connected with CD4+ T cells and dendritic cells, however, EIF4A1 and WDR4 were not substantially correlated with immune cell infiltration in sarcomas." (PMID 36816047, 2023). "However, EIF4A1 and WDR4 were not significantly correlated with immune cell infiltration in sarcomas." (PMID 36816047, 2023).
cancer (54 papers, 2009 to 2026). A tumor composed of atypical neoplastic, often pleomorphic cells that invade other tissues. "We also identified frequent RNA helicase mutations (DDX3X and EIF4A1) in virus-positive tumors spanning multiple cancer types; although DDX3X mutations have been reported in HNSCC141, our results demonstrate their broader relevance across a pan-cancer cohort." (PMID 40595559, 2025). "When looking at individual cancer types, EIF4A1 mutations were significantly more frequent in EBV-positive GC compared to EBV-negative GC (p = 5.95e-3)." (PMID 40595559, 2025). "Dysregulated expression of eIF4A1 has been implicated in several cancers, including breast cancer, melanoma, prostate cancer, and pancreatic ductal adenocarcinoma (PDAC)." (PMID 41299109, 2025). "Inhibitor of Bruton's tyrosine kinase (IBTK) deficiency reduces eIF4A1-dependent oncoprotein expression and neoplastic phenotypes in cancer cells." (PMID 38738857, 2024). "In cell-free systems, EIF4A2 can perform the same functions as EIF4A1, but rarely compensates for the loss of EIF4A1 in cancer cell lines." (PMID 38011999, 2024). "The epigenetic regulation of EIF4A1 transcripts plays an oncogenic role, and the prognosis of patients with cancer is associated with EIF4A1." (PMID 38918785, 2024). "The protein encoded by the EIF4A1 gene is involved in cytoplasmic translation initiation and is an important regulator of cancer." (PMID 36818541, 2023). "Overexpression of NUDT1 in cancer cells makes them more susceptible to carboplatin and triethylenemelamine, and cancer cells expressing higher levels of EIF4A1 were more sensitive to cladribine." (PMID 37089261, 2023). "Matrix metalloproteinase (MMP), cancer metastasis and poor prognosis were also associated with elevated EIF4A1 expression in LUAD patients." (PMID 36101357, 2022). "The gene set positively correlated with EIF4A1 was strongly associated with reduced infiltration of anti-cancer immune cells such as NKT/NK cells and CD4+ T cells, and this accompanied a reduced infiltration score." (PMID 36101357, 2022). "Together, these results suggest that mutations in DDX3X and EIF4A1 may play a role in virus-positive tumors in various types of cancer." (PMID 40595559, 2025). "To elucidate the molecular mechanism underlying BLF1’s selective cytotoxicity toward cancer cells while sparing normal cells at low concentrations, we characterized its effects on the ATPase activities of the eIF4A1 and eIF4A2 proteins using an in-vitro reconstitution system." (PMID 40423315, 2025). "This could explain why EIF4A2 cannot fully compensate for loss of EIF4A1, especially in highly proliferative cell types with high metabolic demands such as GC B cells, which share these features with cancer cells." (PMID 38011999, 2024). "EIF4A1 is associated with cancer cell malignancy, tumor-specific survival, and drug sensitivity." (PMID 36816047, 2023). "Mechanistically, eIF4F promotes pro-SFTPB expression, while pro-SFTPB inhibits the formation of eIF4F complex by binding to eIF4A1, thereby suppressing the translation c-myc and PD-L1 that promote cancer stemness and immune evasion." (PMID 42157944, 2026). "To address these, we developed paralog-specific, affinity-purified rabbit peptide antibodies to investigate the distinct contributions of eIF4A1 and eIF4A2 in cancer biology." (PMID 41299109, 2025). "In conclusion, this study provides a fundamental resource for the cancer research community by finding highly specific antibodies to study eIF4A1 and eIF4A2 at the protein level." (PMID 41299109, 2025). "Enhanced total protein levels and activity of eIF4A1 correlate with poor prognosis and drug resistance in various cancers, including TNBC." (PMID 41299109, 2025). "The development of paralog-specific antibodies for eIF4A1 and eIF4A2 represents a significant advancement in studying their distinct roles in translational control of many hallmarks in cancer biology." (PMID 41299109, 2025).